MIR1246 (microRNA 1246)
Synonyms: hsa-mir-1246; MIRN1246
Gene: MicroRNA gene on chromosome 2 (176,600,980 to 176,601,052, reverse strand). Ensembl gene ENSG00000283203.
Diseases named in the same sentence as MIR1246 in open-access papers:
MIR1246 is named in the same sentence as 5 diseases in open-access papers, as found by Europe PMC text mining. Sharing a sentence is not in itself a finding about the gene and the disease. The quoted sentences say what the papers report.
liver cancer (1 paper, 2020). An epithelial or non-epithelial malignant neoplasm that arises from the liver. "Another study found that octamer 4 activates MIR1246 expression, leading to an increase in the stemness of liver cancer cells." (PMID 32457495, 2020).
pancreatic cancer (1 paper, 2020). "We examined possible associations between serum and urine MIR1246 expression and the clinicopathologic features of pancreatic tumors." (PMID 32457495, 2020). "In addition, in pancreatic cancer cells as well as a mouse model, MIR1246 expression was associated with cancer cell stemness and chemoresistance by targeting cyclin G2 (CCNG2)." (PMID 32457495, 2020). "In this study, we compared the expression of MIR1246 in blood, urine and saliva between patients with pancreatic cancer and healthy controls." (PMID 32457495, 2020). "In the present study, we evaluated the expression of MIR1246 in serum, urine and saliva in patients with pancreatic cancer and examined its potential as a biomarker for pancreatic cancer." (PMID 32457495, 2020). "In the present study, we examined MIR1246 expression as a biomarker of pancreatic cancer." (PMID 32457495, 2020).
cancer (1 paper, 2020). A tumor composed of atypical neoplastic, often pleomorphic cells that invade other tissues. "Significantly higher MIR1246 expression in serum and urine was observed in patients with cancer than in healthy controls." (PMID 32457495, 2020).
MIR1246 also shares sentences with these, for which no sentence is quoted: lymph node metastasis (1 paper); tumor (1).